CXCL12 (C-X-C motif chemokine ligand 12)
Diseases named in the same sentence as CXCL12 in open-access papers (continued):
Sharing a sentence is not in itself a finding about the gene and the disease.
myeloproliferative neoplasm (3 papers, 2021 to 2024). A clonal hematopoietic stem cell disorder, characterized by proliferation in the bone marrow of one or more of the myeloid (i.e., granulocytic, erythroid, megakaryocytic, and mast cell) lineages. "In accordance with these findings, it was shown by another group in myeloproliferative neoplasms that the hematopoietic cells induced a downregulation of the HSPC retention marker CXCL12." (PMID 38893194, 2024).
myositis (3 papers, 2022 to 2023). "Within the inflammatory milieu of myositis, chemokines can activate unique immunomodulatory pathways including B-cell activation and support muscle regeneration with CXCL-12." (PMID 37731487, 2023). "Interestingly, a tissue-specific subpopulation of CD138+ plasma cells and CXCL12+/CXCL13+CD20+ B cells common to ASyS myositis were identified." (PMID 35612662, 2022). "Our findings on muscle specimens from patients with myositis are comparable with inflammatory central nervous system disorders in that increased levels of BAFF, CXCL-12, and CXCL-13 are observed." (PMID 37731487, 2023).
pancreatic neuroendocrine tumor (3 papers, 2022 to 2026). Pancreatic endocrine tumor, also known as pancreatic neuroendocrine tumor (PNET), describes a group of endocrine tumors originating in the pancreas that are usually indolent and benign, but may have the potential to be malignant. "In pancreatic endocrine tumors, CXCL12 is essential for tumor progression." (PMID 36612163, 2022).
parasitemia (3 papers, 2011 to 2015). "Additionally, blocking the CXCR4/CXCL12 interaction causes an increase in circulating parasitemia, suggesting a pivotal role for CXCR4/CXCL12 signaling during malarial infection." (PMID 25909640, 2015). "In the serum of PcAS-infected mice, TNF levels are very high around peak parasitemia, so it is possible that a TNF-modulated reduction in CXCL12 production in the bone marrow is contributing to the observed impaired B lymphopoiesis." (PMID 21687602, 2011).
periodontal disease (3 papers, 2014 to 2023). "CXCL12 levels increase during the development of periodontal disease and may recruit host defense cells to sites of inflammation, which may be involved in activating immune defense pathways during periodontal disease." (PMID 36793719, 2023).
pneumonia (3 papers, 2014 to 2021). An acute, acute and chronic, or chronic inflammation focally or diffusely affecting the lung parenchyma, caused by an infection in one or both of the lungs (by bacteria, viruses, fungi, or mycoplasma.). "They found that ECP can induce the expression of CXCL-12 in airway epithelial cells and then stimulated the migration of fibroblasts to epithelial cells, revealing the role of the CXCL12–CXCR4 axis in mediating ECP-induced fibroblast extravasation in pneumonia." (PMID 34577749, 2021).
pterygium (3 papers, 2018 to 2021). A wedge-shaped fibrovascular lesion arising from the bulbar conjunctiva and extending to the cornea. "The expression of the five hub genes (ECM1, IQGAP2, FN1, GADD34, CXCL12) was determined by real-time PCR in comparisons between 10 normal conjunctival tissues and 10 pterygium tissues." (PMID 32411530, 2020).
rectal tumors (3 papers, 2018 to 2022). "One of the reasons for these discrepancies could be the mixture of colon and rectal tumors in the cohorts and the fact that part of rectal tumors are either irradiated and/or chemically treated before resection, leading to changes in CXCL12 expression level." (PMID 35406582, 2022).
sarcoidosis (3 papers, 2015 to 2024). Sarcoidosis is a multisystemic disorder of unknown cause characterized by the formation of immune granulomas in involved organs. "Multiple immune cell types induced CXCL12/CXCR4 signaling in sarcoidosis, including Th1 T cells, macrophages, and ILCs." (PMID 39225100, 2024). "We conclude that the increased expression of CXCR4 on sarcoidosis-activated immune cells improved cell migration toward CXCL12." (PMID 39225100, 2024). "Moreover, protein immunofluorescence confirmed strong CXCL12 expression within the center of sarcoid granulomas." (PMID 39225100, 2024). "Multiple immune cell types in sarcoidosis-affected skin exhibited increased expression of TLS-specific pathways, including CXCL12/CXCR4 signaling." (PMID 39225100, 2024). "In response to its cognate ligand CXCL12, CD45+ circulating immune cells from sarcoidosis patients exhibited approximately 2-fold greater cell migration compared with CD45+ immune cells from healthy volunteers." (PMID 39225100, 2024). "Finally, CXCL12/CXCR4, a third signaling pathway important for TLS formation, was strongly induced in both non–sarcoidosis- and sarcoidosis-affected skin." (PMID 39225100, 2024).
silicosis (3 papers, 2018 to 2026). Silicosis is a respiratory disease caused by breathing in (inhaling) silica dust. "Combined with our findings that CXCR4 was increased in silicosis lungs and the CXCR4/CXCL12 axis may contribute to the enhancement of cytokines with profibrotic effects." (PMID 34149803, 2021).
T-cell leukemia (3 papers, 2011 to 2020). A malignant disease of the T-lymphocytes in the bone marrow, thymus, and/or blood. "Rapamycin, an inhibitor of mTOR, significantly inhibits CXCL12 mediated migration of both primary human resting T cells and human T cell leukemia cell line CEM." (PMID 21931802, 2011). "The Jurkat T cell leukemia line, which expresses high levels of CXCR4, was incubated with CXCL12 (EC80 at 8 nM) to stimulate calcium flux." (PMID 28526063, 2017).
Waldenström macroglobulinemia (3 papers, 2016 to 2025). "CXCL12 is a major chemoattractant in B cell malignancies, including Waldenström’s macroglobulinemia (WM)." (PMID 40394646, 2025).
ZIKV infection (3 papers, 2019 to 2024). "The process is mediated by the upregulation of C-X-C motif chemokine 12 (CXCL12) in monocyte during ZIKV infection, a key regulator of lymphocytes shifts across BBB into CNS parenchyma as it interacts with C-X-C chemokine receptor type 4 (CXCR4)." (PMID 35308394, 2022). "Firstly, the main targets of ZIKV infection in humans, CD14+CD16+ monocytes strongly produce the chemokine CXCL12/SDF-1 and the cytokine IL-6." (PMID 39599813, 2024). "We show that ZIKV infection activates proinflammatory (IL-1β) cytokines as well as chemokines (CCL2, CCL5, GM-CSF, G-CSF, CXCL1, and CXCL12) in the endothelial cells." (PMID 31249527, 2019).
abortion (2 papers, 2015 to 2024). the ending of pregnancy by removing a fetus or embryo before it can survive outside the uterus. "Significantly upregulated CXCL12 and CXCR4 expression was detected in the uteri of IFN-γ-induced abortion mice in vivo, and CXCL12 facilitated peripheral CD49b+ NK cell migration in vitro (data not shown), suggesting an association between CXCL12 and IFN-γ-induced abortion." (PMID 26655673, 2015). "Nevertheless, when pretreated with LDN57444, an inhibitor of UCHL1, the expression of CXCL12, IL15 and TGF-β in normal DSCs was significantly decreased, as well as their ability to recruit and educate dNKs, which were similar to that of the abortion DSCs." (PMID 38769534, 2024). "Notably, CXCL12, IL15 and TGF-β were significantly downregulated in abortion DSCs, consequently leading to a substantial decrease in dNK percentage in the coculture assay with abortion DSCs." (PMID 38769534, 2024). "Overall, our findings suggest that although CXCL12 correlates with IFN-γ-induced abortion, the alteration in Ly-49 receptor expression is not dependent on CXCL12." (PMID 26655673, 2015).
acute graft versus host disease (2 papers, 2010 to 2022). A syndrome of immunologically mediated tissue damage that may occur following an allogeneic transplant, usually affecting the skin, liver, and GI tract. "A predictive model using five of such polymorphisms (CXCL12 rs2839695, IL12A rs7615589, KIR3DL1 rs4554639, TGFB2 rs5781034 for the recipient and CD48 rs2295615 for the donor) together with the development of acute GVHD grade III/IV improved risk stratification of CMV reactivation." (PMID 35525883, 2022).
alcohol use disorder (2 papers, 2021). "Plasmatic reduction of the levels of SDF-1/CXCL12 has been described in patients with alcohol use disorders." (PMID 34638483, 2021).
anaplastic thyroid cancers (2 papers, 2014 to 2018). "The absence of CXCL12 in non-cancerous thyroid lesions and in other thyroid malignancies, such as medullary and anaplastic thyroid cancers, supported the opinion that CXCL12 is specifically associated with PTC." (PMID 29977225, 2018).
aortic valve stenosis (2 papers, 2014 to 2022). Aortic valve stenosis (AVS) is a condition characterized by narrowing of the heart's aortic valve opening. "CXCL12/CXCR4 signaling is essential in cardiac development and repair, however, its contribution to aortic valve stenosis (AVS) remains unclear." (PMID 36148060, 2022).
astrogliomas (2 papers, 2020 to 2023). "Among various chemokine receptors and their ligands tested, mRNA expression of both CXCL12 and CXCR4 were identified in the highest percentage of human astrocytic tumor samples." (PMID 32456359, 2020).
bone sarcoma (2 papers, 2018 to 2021). A sarcoma that arises from the bone. "In bone sarcomas, the binding of CXCL12 to CXCR7 can activate the PI3K-Akt-NF-κΒ and MEK-ERK-IKKαβ-NF-κΒ pathways, which regulates the proliferation/survival as well as the migration/metastasis of tumor cells." (PMID 30574021, 2018). "Furthermore, as a potential target in OS treatment, CXCL12 has been proved to participate in the progression and metastasis of bone sarcomas." (PMID 34225733, 2021).
brain inflammation (2 papers, 2012 to 2023). "This indicated that CXCL12 is generated by the BBB to attract lymphocytes, as was shown before in brain inflammations." (PMID 36631780, 2023).
bullous pemphigoid (2 papers, 2022 to 2024). Bullous pemphigoid (BP) is the most common form of autoimmune bullous dermatosis. "The CXCR4/CXCL12 axis seems particularly associated with B-cells infiltration in single-cell analysis of SSc skin biopsies and is also involved in cutaneous B-cell infiltration in bullous pemphigoid." (PMID 39185406, 2024).
bursitis (2 papers, 2019). Inflammation or irritation of a synovial bursa, the fibrous sac that acts as a cushion between moving structures of bones, muscles, tendons or skin. "Increased levels of SDF1 (CXCL12) can be seen in inflammatory conditions, such as sub-acromial bursitis and acute liver injury." (PMID 31366318, 2019).
Cachexia (2 papers, 2019). Severe weight loss, wasting of muscle, loss of appetite, and general debility related to a chronic disease. "More specifically, the quantitative modulation of the CXCL12 signaling axis has already been shown to influence the kinetics and efficiency of muscle regeneration, and the volumetric muscle loss of age-associated cachexia." (PMID 31533830, 2019). "Our prediction analyses also revealed microRNA miR-17 as an important regulator of transcripts, such as Cxcl12, Mef2c, Stat3, and Cav1, that are translated into proteins with a role in cancer cachexia." (PMID 31013615, 2019). "Our results also show protein–protein interactions of Cxcl12 with the metalloprotease Mmp, suggesting that this interaction could affect muscle regeneration and extracellular matrix remodeling in cancer cachexia." (PMID 31013615, 2019). "Finally, we found drugs targeting MSTN, CXCL12, and CAMK2B, which may be considered for the development of novel therapeutic strategies for cancer-related cachexia." (PMID 31013615, 2019).
congenital heart defect (2 papers, 2020 to 2025). "Consistently, CXCL12 was found to be overexpressed in the SMC layer of pulmonary vessels from patients with PAH–congenital heart disease." (PMID 40345592, 2025).
coronary atherosclerosis (2 papers, 2014 to 2024). Atherosclerosis of the coronary vasculature. "We also found significant associations between the GREX of CXCL12 and coronary atherosclerosis in individuals of African genetic ancestry (n=12, 314, p=0.0035)." (PMID 39483879, 2024).
dyslipidaemia (2 papers, 2021). "CXCL12 levels also have an inverse relationship with HDL-C levels, but the exact role of CXCL12 in regulating dyslipidaemia is still unclear." (PMID 34494495, 2021). "CXCL12 is considered proatherogenic because of its involvement in dyslipidaemia, angiogenesis, plaque destabilization, thrombus formation, neointimal hyperplasia, and proinflammatory effects on the vascular endothelium." (PMID 34494495, 2021). "In addition increased serum CXCL12 levels are found in patients with dyslipidaemia, and statins used for the treatment of dyslipidaemia have been shown to reduce CXCL12 levels (probably through ACKR3), implicating the CXCL12/ACKR3 axis as a potential therapeutic target." (PMID 34494495, 2021).
erectile dysfunction (2 papers, 2020 to 2023). Persistent or recurrent inability to achieve or to maintain an erection during sexual activity. "Periurethral injection of CXCL-12 was feasible and improved both urinary incontinence and erectile dysfunction and suggests." (PMID 32161689, 2020).
gastric adenocarcinoma (2 papers, 2021). "Based on the IHC score of Wnt5a and CXCL12 expression in the GC area and adjacent fibroblast area, CXCL12CAF expression was significantly higher than CXCL12 in gastric adenocarcinoma (P<0.001)." (PMID 33854601, 2021). "Specifically, our case would suggest an involvement of the CXCL12 (SDF-1)/CXCR4 axis in the observed metastasis of DLBCL to primary gastric adenocarcinoma." (PMID 34187383, 2021).
gestational diabetes mellitus (2 papers, 2023 to 2024). "In a human study, serum levels of angiogenic (CXCL1 and CXCL12) were higher in gestational diabetes mellitus mothers (GDMM)." (PMID 37928902, 2023).
glomerulonephritis (2 papers, 2021 to 2024). A renal disorder characterized by damage in the glomeruli. "Moreover, in NZB/NZW mouse lupus immune complex nephritis, blocking CXCL12 can prevent glomerulonephritis by decreasing autoantibody production and T cell recruitment by glomeruli." (PMID 38716725, 2024).
HCMV infection (2 papers, 2012 to 2013). "HCMV infection significantly increased mRNA and total cell surface expression of the two known receptors for CXCL12: CXCR4 and CXCR7." (PMID 23116176, 2012). "In this study, the effect of HCMV infection on the CXCL12-mediated migration and invasion of the EVT cell line SGHPL-4 was investigated." (PMID 23116176, 2012). "HCMV dysregulation of placental function associated with pregnancies complicated by primary HCMV infection is mediated in part through a mechanism that involves inhibition of EVT migration and invasion induced by CXCL12." (PMID 23116176, 2012). "HCMV infection significantly decreased the concentration of CXCL12 in the supernatants at 24, 48, 72, and 96 hours post-infection (p<0.05)." (PMID 23116176, 2012). "Collectively, these studies demonstrate that CXCL12 is sequestered during HCMV infection in placental cells and that HCMV inhibits EVT migration and invasion." (PMID 23116176, 2012). "SGHPL-4 cell invasion through Matrigel toward CXCL12 at both 50 ng/ml and 10 ng/ml was also significantly impaired following HCMV infection (p<0.001), again recapitulating the weak background migration toward serum-free culture medium." (PMID 23116176, 2012). "Despite recruitment of CXCR4 and CXCR7 to the cell membrane, both migration and invasion toward CXCL12 were almost completely inhibited following HCMV infection." (PMID 23116176, 2012). "HCMV infection blocked migration toward recombinant human CXCL12 at both 50 ng/ml and 10 ng/ml (p<0.001) to the level seen in negative control wells containing serum-free culture medium alone." (PMID 23116176, 2012). "This suggests that the decrease in CXCL12 secretion seen following HCMV infection is a function of decreased release or degradation of preformed chemokine, rather than altered generation of new transcripts or protein." (PMID 23116176, 2012). "Given perinuclear sequestration and decreased secretion of CXCL12 following HCMV infection of SGHPL-4 cells, the abundance and distribution of the CXCL12 receptors, CXCR4 and CXCR7, were also analyzed." (PMID 23116176, 2012). "The aim of this study was to determine the effect of HCMV infection on cellular distribution and expression of CXCL12 and its receptors, CXCR4 and CXCR7, and on EVT migration and invasion in response to CXCL12." (PMID 23116176, 2012). "Given the decreased secretion of CXCL12 following HCMV infection of SGHPL-4 cells, it is possible that HCMV-infected cells upregulate cell surface and mRNA expression of CXCR4 and CXCR7 as an attempt to compensate for lack of or dysregulated autocrine signaling." (PMID 23116176, 2012). "If CXCR7 in fact acts as a chemokine sink, upregulation of this receptor to the cell surface may mediate sequestration of CXCL12 following HCMV infection." (PMID 23116176, 2012). "HCMV infection induced upregulation of SCF, CXCL12 and IL8, which was unaltered after transfection with the control siRNA." (PMID 23861869, 2013). "Blockade of CXCR4 function with a neutralizing antibody (12G5) partially inhibited migration and invasion toward CXCL12, but to a lesser extent than the inhibition seen following HCMV infection, suggesting that both CXCR4 and CXCR7 may mediate migration and invasion in response to CXCL12." (PMID 23116176, 2012).
helminth infection (2 papers, 2012 to 2022). "The L. sigmodontis filarial infection is a Th2-based helminthiasis and the CXCL12/CXCR4 axis has been reported to have a role in numerous Th2-based inflammatory diseases." (PMID 22511975, 2012).
Idiopathic Thrombocytopenic Purpura (2 papers, 2016 to 2017). "In the onset and development of childhood Idiopathic Thrombocytopenic Purpura, the polymorphism of SDF-1 (CXCL12) gene may be implicated." (PMID 28589131, 2017).
immunodeficiency syndrome (2 papers, 2016 to 2021). "Severe HPV infections characterize the wart, hypogammaglobulinemia, infection, and myelokathexis (WHIM) immunodeficiency syndrome, which is caused by gain-of-function mutations in the CXCR4 receptor for the CXCL12 chemokine, one of which is CXCR41013." (PMID 27918748, 2016).
infertile (2 papers, 2013 to 2017). "CXCL12 or other CXCR4 receptor agonists may be useful in the treatment of infertility or adverse pregnancy outcomes in Asherman’s syndrome and other related uterine disorders." (PMID 28345002, 2017).
interstitial lung disease (2 papers, 2011 to 2012). A diverse group of lung diseases that affect the lung parenchyma. "A similar increase in plasma CXCL12 levels in patients with interstitial lung disease, supporting the concept that there is a CXCL12 gradient between the bone marrow and the blood to allow release of fibrocytes from the bone marrow in these patients." (PMID 23259468, 2012). "Compared with controls, patients with interstitial lung disease had extensive expression of CXCL12 in lung and plasma." (PMID 21219601, 2011). "Are fibrocytes and CXCL12/CXCR4 relevant to human interstitial lung disease?" (PMID 23259468, 2012). "CXCL12 was detectable in the bronchoalveolar fluid in 40% of patients with interstitial lung disease, whereas none was detected in normal controls." (PMID 21219601, 2011). "In addition, the chemokine ligand, CXCL12, was found to be extensively expressed in lung tissue from patients with the histologically diagnosed interstitial lung disease as detected by immunohistochemistry and ELISA, but not in histologically normal lungs." (PMID 23259468, 2012).
intestinal cancer (2 papers, 2023 to 2025). "Cochrane’s Q test did not provide evidence of heterogeneity between CCL14 (p = 0.768, p = 0.808), CCL22 (p = 0.502), CCL28 (p = 0.175), CXCL12 (p = 0.530) and CXCL14 (p = 0.534) and intestinal cancer." (PMID 38075694, 2023).